CHRM1 (cholinergic receptor muscarinic 1)
Description:
The muscarinic acetylcholine receptor mediates various cellular responses, including inhibition of adenylate cyclase, breakdown of phosphoinositides and modulation of potassium channels through the action of G proteins. Primary transducing effect is Pi turnover.
Synonyms: HM1; M1; M1R
Tractability: Small molecule: an approved drug acts on it; a structure with a bound ligand is known; a high-quality ligand is known; it belongs to a druggable protein family. Antibody: its Gene Ontology location is reachable by antibodies, with high confidence; UniProt places it where antibodies can reach, with medium confidence; UniProt predicts a signal peptide or a membrane-spanning region. PROTAC: its protein half-life has been measured; a small molecule that binds it is known.
Target class: Small molecule receptor (family A GPCR); Acetylcholine receptor; Monoamine receptor; Family A G protein-coupled receptor; Membrane receptor
Chemical probes: CHEMBL2377385, CHEMBL3616501, ML012, ML137, ML169, MSD-M1PAM (high quality), VU 0357017 hydrochloride
Safety:
Unwanted effects reported when the protein is acted on. In parentheses: how it was acted on, where the effect was seen, and who reports it.
blurred vision (Bowes et al. (2012): inhibition, cardiovascular system, central nervous system, gastrointestinal; Lynch et al. (2017): inhibition, acute dosing and activation, acute dosing, nervous system, respiratory, liver, cardiovascular, gastrointestinal)
decreased cognitive function (Bowes et al. (2012): inhibition, cardiovascular system, central nervous system, gastrointestinal; Lynch et al. (2017): inhibition, acute dosing, nervous system, respiratory, liver, cardiovascular, gastrointestinal)
decreased gastric acid secretion (Bowes et al. (2012): inhibition, cardiovascular system, central nervous system, gastrointestinal; Lynch et al. (2017): inhibition, acute dosing, nervous system, respiratory, liver, cardiovascular, gastrointestinal)
increased gastric acid secretion (Lynch et al. (2017): activation, acute dosing, nervous system, respiratory, liver, cardiovascular, gastrointestinal; Bowes et al. (2012): activation, cardiovascular system, central nervous system, gastrointestinal)
increased heart rate (Lynch et al. (2017): inhibition, acute dosing, nervous system, respiratory, liver, cardiovascular, gastrointestinal; Urban et al. (2012): activation, cardiovascular system, nervous system, gastrointestinal)
abdominal cramps (activation, acute dosing; nervous system, respiratory, liver, cardiovascular, gastrointestinal; source: Lynch et al. (2017))
acidosis (activation, acute dosing; nervous system, respiratory, liver, cardiovascular, gastrointestinal; source: Lynch et al. (2017))
bronchorrhea (activation, acute dosing; nervous system, respiratory, liver, cardiovascular, gastrointestinal; source: Lynch et al. (2017))
bronchospasm (activation, acute dosing; nervous system, respiratory, liver, cardiovascular, gastrointestinal; source: Lynch et al. (2017))
centrilobular liver congestion (activation, acute dosing; nervous system, respiratory, liver, cardiovascular, gastrointestinal; source: Lynch et al. (2017))
cough (activation, acute dosing; nervous system, respiratory, liver, cardiovascular, gastrointestinal; source: Lynch et al. (2017))
decreased convulsions (inhibition, acute dosing; nervous system, respiratory, liver, cardiovascular, gastrointestinal; source: Lynch et al. (2017))
decreased locomotor activity (activation, acute dosing; nervous system, respiratory, liver, cardiovascular, gastrointestinal; source: Lynch et al. (2017))
decreased memory (inhibition, acute dosing; nervous system, respiratory, liver, cardiovascular, gastrointestinal; source: Lynch et al. (2017))
decreased pupil diameter (activation, acute dosing; nervous system, respiratory, liver, cardiovascular, gastrointestinal; source: Lynch et al. (2017))
disruption of cognitive functions such as learning and memory (inhibition; cardiovascular system, nervous system, gastrointestinal; source: Urban et al. (2012))
exhaustion (activation, acute dosing; nervous system, respiratory, liver, cardiovascular, gastrointestinal; source: Lynch et al. (2017))
frothing (activation, acute dosing; nervous system, respiratory, liver, cardiovascular, gastrointestinal; source: Lynch et al. (2017))
gastrointestinal side effects (activation; cardiovascular system, nervous system, gastrointestinal; source: Urban et al. (2012))
hypertension (activation; cardiovascular system, central nervous system, gastrointestinal; source: Bowes et al. (2012))
hyperthermia (activation; cardiovascular system, central nervous system, gastrointestinal; source: Bowes et al. (2012))
increased blood pressure (activation; cardiovascular system, nervous system, gastrointestinal; source: Urban et al. (2012))
increased body temperature (activation, acute dosing; nervous system, respiratory, liver, cardiovascular, gastrointestinal; source: Lynch et al. (2017))
increased convulsions (activation, acute dosing; nervous system, respiratory, liver, cardiovascular, gastrointestinal; source: Lynch et al. (2017))
increased locomotor activity (inhibition, acute dosing; nervous system, respiratory, liver, cardiovascular, gastrointestinal; source: Lynch et al. (2017))
increased memory (activation, acute dosing; nervous system, respiratory, liver, cardiovascular, gastrointestinal; source: Lynch et al. (2017))
increased respiratory rate (activation, acute dosing; nervous system, respiratory, liver, cardiovascular, gastrointestinal; source: Lynch et al. (2017))
increased salivation (activation, acute dosing; nervous system, respiratory, liver, cardiovascular, gastrointestinal; source: Lynch et al. (2017))
increased sympathetic outflow (activation; cardiovascular system, nervous system, gastrointestinal; source: Urban et al. (2012))
increased/decreased blood pressure (activation, acute dosing; nervous system, respiratory, liver, cardiovascular, gastrointestinal; source: Lynch et al. (2017))
and 12 more effects
Gene: Protein-coding gene on chromosome 11 (62,908,679 to 62,921,877, reverse strand). Ensembl gene ENSG00000168539.
Subcellular location: Cell membrane; Postsynaptic cell membrane
Pathways (Reactome):
Signal Transduction: G alpha (q) signalling events; Muscarinic acetylcholine receptors
Gene Ontology:
Molecular function: protein binding; G protein-coupled acetylcholine receptor activity; phosphatidylinositol-4,5-bisphosphate phospholipase C activity; G protein-coupled receptor activity
Biological process: positive regulation of monoatomic ion transport; adenylate cyclase-inhibiting G protein-coupled acetylcholine receptor signaling pathway; chemical synaptic transmission; G protein-coupled acetylcholine receptor signaling pathway; G protein-coupled receptor signaling pathway; G protein-coupled receptor signaling pathway, coupled to cyclic nucleotide second messenger; nervous system development; phospholipase C-activating G protein-coupled acetylcholine receptor signaling pathway; phospholipase C-activating G protein-coupled receptor signaling pathway; regulation of glial cell proliferation; signal transduction; acetylcholine receptor signaling pathway; cognition; neuromuscular synaptic transmission; positive regulation of intracellular protein transport; postsynaptic modulation of chemical synaptic transmission; regulation of locomotion; regulation of postsynaptic membrane potential; saliva secretion
Cellular component: dendrite; membrane; plasma membrane; synapse; asymmetric synapse; axon terminus; cholinergic synapse; glutamatergic synapse; postsynaptic density membrane; postsynaptic membrane; presynaptic membrane; Schaffer collateral - CA1 synapse
Genetic constraint (gnomAD): Loss-of-function variants: 5 observed, 32.37 expected, observed/expected ratio (o/e) 0.15, 90% interval 0.08 to 0.32. The upper end of that interval is the gene's LOEUF score, 0.32, which puts it in group 1 of 6, group 1 being the genes least tolerant of losing a copy. Missense variants: 338 observed, 634.16 expected, observed/expected ratio (o/e) 0.53, 90% interval 0.49 to 0.58. Synonymous variants: 227 observed, 260.2 expected, observed/expected ratio (o/e) 0.87, 90% interval 0.78 to 0.97.
Homologues: Orthologues: chimpanzee CHRM1 (100% identical), macaque CHRM1 (99% identical), mouse Chrm1 (99% identical), rat Chrm1 (99% identical), dog CHRM1 (98% identical), guinea pig CHRM1 (96% identical), tropical clawed frog chrm1 (63% identical), zebrafish chrm1a (53% identical). Paralogues in human: CHRM3 (56% identical), CHRM5 (53% identical), CHRM4 (43% identical), CHRM2 (42% identical), HRH1 (26% identical), HRH3 (24% identical), DRD4 (23% identical), HTR1A (23% identical), DRD5 (22% identical), DRD3 (21% identical), HTR4 (21% identical), DRD1 (20% identical), and 13 more.
Diseases named in the same sentence as CHRM1 in open-access papers:
CHRM1 is named in the same sentence as 91 diseases in open-access papers, as found by Europe PMC text mining. Sharing a sentence is not in itself a finding about the gene and the disease. The quoted sentences say what the papers report.
schizophrenia (15 papers, 2013 to 2025). A major psychotic disorder characterized by abnormalities in the perception or expression of reality. "Further research on these targets showed that abnormally expressed Chrm1 is associated with various neurological disorders, including surgical menopause, Huntington’s disease, and memory function in schizophrenia." (PMID 39861162, 2025). "Here, because of the focus on schizophrenia, we will review the data pertinent to CHRM1 and CHRM4 as these are now implicated in the molecular pathology and treatment of the disorder." (PMID 36909280, 2023). "Pathways and proteins affected by the changes in cortical gene expression in the Chrm1−/− are linked to the molecular pathology of schizophrenia." (PMID 34521861, 2021). "Based on these data, we postulated that some changes in cortical gene expression in patients with schizophrenia would be associated with lower levels of CHRM1 signalling." (PMID 34521861, 2021). "Chrm1 encodes a receptor that is highly expressed in glutamatergic neurons and in postsynaptic regions of the hippocampus, and is a potential target molecule for schizophrenia treatment." (PMID 38139000, 2023). "However, based on findings using DNA from blood, there may be an association between genotype at a 267C/C single nucleotide polymorphism in the CHRM1 gene and cognitive functioning in schizophrenia." (PMID 36909280, 2023). "Whilst it has long been argued that CHRM1 plays an important role in the pathology of schizophrenia, recent findings suggest the receptor is important in regulating diverse functions that are affected in those with the disorder." (PMID 36909280, 2023). "In relation to the systemic illnesses more prevalent in people with schizophrenia, recent reports of the presence of CHRM1 on the pancreas and as a suggested drug target for the treatment of gastrointestinal and liver diseases are of interest." (PMID 36909280, 2023). "In this study, those with the schizophrenia had approximately a 2.5-fold lower level of CHRM1/CHRM4 in the frontal, striatal, temporal, and occipital cortex compared to controls." (PMID 36909280, 2023). "Finally, and somewhat surprisingly, the CHRM1–/– mouse has developmental abnormalities in the auditory cortex which raises the intriguing possibility that a deficit in CHRM1 may be involved in the increase in hearing loss in people with schizophrenia." (PMID 36909280, 2023). "Taken together, data from postmortem CNS show there are lower levels of CHRM1/CHRM4 in some people with schizophrenia." (PMID 36909280, 2023). "These exciting new developments around targeting CHRM1 and 4 to treat schizophrenia mean it is timely to review the role for CHRMs in the molecular pathology and treatment of the disorder." (PMID 36909280, 2023). "This study added to an earlier study using 123I-IDEX SPECT that reported lower levels of CHRM1/CHRM4 in people with schizophrenia who were being treated with risperidone." (PMID 36909280, 2023). "Using analogous technology allowed us to better compare changes in gene expression in the cortex from Chrm1−/− mice and patients with schizophrenia." (PMID 34521861, 2021). "Our findings argue CHRM1-mediated changes in gene expression are relevant to the pathophysiologies of schizophrenia and Alzheimer’s disease and the maintenance of cognitive ability in humans." (PMID 34521861, 2021). "Our human cortical gene expression data showed 47 genes had altered expression in Chrm1−/− mouse and the frontal pole from patients with schizophrenia with the change in expression of 44 genes being in opposite directions." (PMID 34521861, 2021). "By contrast, there were no genes that had changed levels of expression in the cortex of Chrm1−/− mice and BA 9 or BA 33 from patients with schizophrenia." (PMID 34521861, 2021). "Post-mortem studies have reported that the expression of miR-107, a miRNA that targets the CHRM1 sequence, is increased in schizophrenia." (PMID 29657307, 2018).
schizophrenia (continued). "Deficits in cortical muscarinic M1 receptor (CHRM1) protein have been identified in a sub-group of over a quarter of individuals with schizophrenia." (PMID 29657307, 2018). "In schizophrenia, subjects with deficits in CHRM1 protein expression also show a reduction in cortical and subcortical binding of [3H]AF-DX 384, a CHRM2/CHRM4 selective radioligand." (PMID 23805071, 2013). "In schizophrenia, post-mortem studies of the cortex point to the involvement of CHRM1, with the recent identification of a sub-type of schizophrenia with widespread loss of cortical and sub-cortical CHRM1 protein expression." (PMID 23805071, 2013). "Chrm1 is related to various psychiatric disorders, including schizophrenia and mood disorders." (PMID 38139000, 2023). "In patients with schizophrenia, the expression of Chrm1 is decreased in the cortex." (PMID 38139000, 2023). "The initial neuroimaging study of CHRMs in schizophrenia used 123I-IQNB SPECT to show there were lower levels of CHRM1/CHRM4 (30% in the striatum and 20% in frontal and temporal regions) in the CNS of drug-free people with the disorder compared to matched control subjects." (PMID 36909280, 2023). "The identification of MRDS has enabled studies to compare its molecular pathology to schizophrenia where there is no determinable loss of cortical CHRM1 (non-MRDS)." (PMID 36909280, 2023). "The notion of sub-group specific changes in CHRM1-related biochemistry has recently been suggested to account for changes in the coupling of CHRM1 to Gα q/11 in the dorsolateral prefrontal cortex of people with schizophrenia." (PMID 36909280, 2023). "Hence, as it is increasingly recognized the molecular pathology of diseases of the human CNS extend into the periphery, it will be important to consider if CHRM1-mediated pathophysiology in disorders such as schizophrenia also extends beyond the CNS." (PMID 36909280, 2023). "More recent research has attempted to address some of the limitations of the early studies on CHRMs in schizophrenia by measuring CHRM1/CHRM4 using SPECT and 123I-IDEX binding in 30 medication-free people who were diagnosed with a psychotic disorder and were in the early phase of the disease." (PMID 36909280, 2023). "However, our study in the Chrm1−/− has revealed opposing changes in levels of most of the genes that are also changed in BA 10 from patients with schizophrenia." (PMID 34521861, 2021). "Moreover, existing data implicates 26 of these genes with changed levels of expression in Chrm1−/− mouse to the pathophysiology of schizophrenia, further arguing the changes in cortical gene expression in the Chrm1−/− mouse are not purely due to chance." (PMID 34521861, 2021). "Hence, it is significant that approximately 25% of people with schizophrenia could be separated into a sub-group, termed the CHRM deficit sub-group (MRDS), because they have a marked loss of cortical CHRM1." (PMID 36909280, 2023). "A summary of differential findings relating to the molecular pathology of a sub-group of people with schizophrenia and a marked loss of cortical CHRM1 (MRDS) and other people with schizophrenia who do not have a marked loss of cortical CHRM1 (non-MRDS) compared to controls." (PMID 36909280, 2023). "Hence, the studies showing lower levels of [3H]pirenzepine binding in people with schizophrenia where the incubation time was short argue the decreased radioligand binding would be due to lower levels of CHRM1." (PMID 36909280, 2023). "Hence, this review will focus on the data supporting a role for the CHRM1 and CHRM4 in the molecular pathology of schizophrenia and the physiological processes that are affected by the changes in CHRM1 and CHRM4 signaling that would be postulated to be occurring in people with the disorder." (PMID 36909280, 2023). "However, it does point to a novel mechanism of CHRM1 regulation that may be useful for further characterising the factors contributing to this sub-type of schizophrenia." (PMID 29657307, 2018).